RN7SL526P (RNA, 7SL, cytoplasmic 526, pseudogene)
Gene: Miscellaneous RNA gene on chromosome 19 (58,069,970 to 58,070,288, forward strand). Ensembl gene ENSG00000243642.
Homologues: Orthologues: chimpanzee Metazoa_SRP (98% identical). Paralogues in human: RN7SL33P (80% identical), RN7SL317P (77% identical), Metazoa_SRP (76% identical), RN7SL775P (76% identical), Metazoa_SRP (75% identical), RN7SL487P (73% identical), RN7SL40P (70% identical), RN7SL1 (69% identical), RN7SL357P (69% identical), RN7SL156P (69% identical), RN7SL2 (69% identical), RN7SL733P (68% identical), and 698 more.